KRT20 (keratin 20)
Diseases named in the same sentence as KRT20 in open-access papers (continued):
Sharing a sentence is not in itself a finding about the gene and the disease.
tumor (continued). "Conversely, KRT20 is expressed in differentiated cells of the tumour core." (PMID 33673710, 2021). "The authors elucidated that differentiated tumor cells characterized by expression of KRT20, could revert to LGR5+ cells, to fuel tumor growth." (PMID 34095127, 2021). "Multivariate cox proportional hazard analysis of DSS revealed that the combination of BIRC5 and KRT20 mRNA to predict outcome was an independent prognostic factor, when age, sex, BMI, tumor stage, grade, and node status were included in the analysis (p = 0.0167)." (PMID 33050010, 2020). "Additionally, the proliferation of KRT20+ and differentiated tumor cells occurred simultaneously with tumor regeneration." (PMID 31317205, 2019). "Also in this case, an initial compensatory proliferation of remaining LGR5−/KRT20+ cells is observed, but it is insufficient to ensure tumor volume maintenance." (PMID 29853913, 2018). "For some cultures, variation in cytokeratin 20 expression for individual spheroids obtained from the same tumour could be observed." (PMID 28877221, 2017). "Since the immunohistochemical analysis was negative for the thyroid transcription factor-1 protein (TTF-1) and was positive for cytokeratin 20, a primary adenocarcinoma of the lung was unlikely and the tumour was finally attributed to the minor salivary glands as site of origin." (PMID 18667060, 2008). "This was expected as oncogene-enriched subtype tumours exhibited more aggressive tumour growth and had an increased expression of gene mutations involved in cell proliferation (ERBB2, SLC44A4, EPCAM, CLDN3, and CLDN4), cell differentiation (ELF3 and GPX2), and mucin production (KRT20)." (PMID 36723696, 2023). "Loss of cytokeratin 20 (CK20) has been associated with older age (above 56 years), right-sided tumours, higher grade and mucinous histology, advanced stage, increased intertumoral lymphocytic infiltration (creating Crohn’s disease-like infiltrate) compared with CK20-positive tumours." (PMID 35055034, 2022). "Moreover, 24% of the tumours completely lost KRT20 mRNA expression below the limit of detection." (PMID 34073233, 2021). "Furthermore, some studies show an association between the high expression of luminal markers such as KRT20 and high tumor stage, grade and micrometastasis, which are known to be associated with worse survival, which further indicates a luminal patient group with impaired survival." (PMID 32252315, 2020). "Furthermore KRT20 was significantly lower expressed in CDKN2Ahigh tumours (p = 0.028)." (PMID 30258198, 2018). "This delayed differentiation fits in well with the observation that LGR5+ and KRT20+ tumor cells reside in complementary compartments rather than intermingled in the same area and may suggest that distinct tumor niches facilitate stem or differentiation states." (PMID 28468934, 2017). "Immunohistochemical analysis of 1882 tumours from nine independent CRC cohorts revealed that SATB2 was expressed in 85% of all tumours, suggesting the utility of SATB2 as a diagnostic marker for CRC, particularly when used in combination with cytokeratin 20 (CK20)." (PMID 22333599, 2012). "After differentiation, the fraction of cells expressing colon epithelium-specific cytokeratin 20 increased significantly (∼90% compared with 26%), whereas BrdU incorporation was observed in ∼40% of differentiated cells compared with ∼10% of undifferentiated tumour spheroid cells." (PMID 20332776, 2010). "Of the LG xenografts, 79% and 78% displayed positive staining for VIL1 and KRT20, respectively, compared to 12% and 33% of HG tumours (P < 0.001 and P < 0.0001, for VIL1 and KRT20 respectively, Fisher’s exact test)." (PMID 40473896, 2025). "The tumor cells exhibited positivity for cytokeratin 7 (CK7) and caudal type homeobox 2 (CDX-2) but negativity for cytokeratin 20 (CK20), paired box 8 (PAX8), NK3 homeobox 1 (NKX3.1), and thyroid transcription factor 1 (TTF-1)." (PMID 39350874, 2024).
tumor (continued). "Immunohistochemically, the tumor was positive for AE1/AE3, cytokeratin 7, and cytokeratin 20, indicating that it had originated from the urothelium." (PMID 38524652, 2024). "Tumor xenografts at experimental endpoint showed reduced SMARCB1 and elevated KRT20 mRNA expression by RT-PCR." (PMID 38472198, 2024). "Luminal tumours were identified as KRT20+/GATA3+/FOXA1+ and basal tumours as KRT5/6+/KRT14+/GATA3−/FOXA1−." (PMID 39594166, 2024). "Consistent with previous reports, all H&E-positive tumor sections stained for ATOH1 (7 of 7) and most for KRT20 (5 of 7)." (PMID 36719743, 2023). "The heterogeneous expression of KRT20 and WNT signaling activity demonstrates a high degree of intra-tumor heterogeneity present in these tumors." (PMID 36077793, 2022). "The immunohistochemistry staining showed immunoreactivity to keratin 20 (CK20) in the sections of tumors from miBx, miPa, and miPk cells while only miPk tumor sections were immunoreactive to keratin 7 (CK7)." (PMID 35063003, 2022). "Histological examination revealed that HCT116EHF + CDX1 tumours were more differentiated, evidenced by increased gland formation and expression of the differentiation markers VIL1 and KRT20, compared to HCT116EV, HCT116EHF or HCT116CDX1 tumours." (PMID 35606410, 2022). "In the present study, high ERBB2 expression correlated significantly with an elevated KRT20 expression indicative of luminal tumours and with a lower KRT5 expression as a marker for basal tumours." (PMID 34073233, 2021). "The H&E staining and 11 IHC markers (Ki67, P63, GATA3, KRT5/6, KRT20, E-cadherin, 34βE12, PD-L1, EGFR, Nectin4, and HER2) were used to evaluate tumor phenotype maintenance." (PMID 35432811, 2021). "Formalin-fixed paraffin-embedded tumour tissue samples from TUR-BT of 54 patients (42 males, 12 females, median age of 64) with MIBC were analyzed for KRT20, KRT5, ESR1, and ERBB2 mRNA expression." (PMID 34073233, 2021). "Tumours were considered as luminal type if they had a high expression of ERBB2, ESR1, or KRT20 while showing a low expression of KRT5." (PMID 34073233, 2021). "As the overall expression across all tumours and subtypes revealed differences for KRT20, ERBB2, and ESR1 mRNA expression, the potential predictive value of the target gene expression of KRT20, ERBB2, and ESR1 was further analysed by partitioning test." (PMID 34073233, 2021). "Usefulness of molecular techniques for detecting tumor markers, such as carcinoembryonic antigen (CEA), cytokeratin 19 (CK-19), and cytokeratin 20 (CK-20), have been reported." (PMID 32992913, 2020). "Similarly, positive immunostaining for cytokeratin 20 (CK20), the protein encoded by the Keratin 20 (KRT20) gene, was observed in the cytoplasm and/or cell membrane of the PDCOs and the abundance of CK20+ cells closely resembled that of the patient-matched primary tumour." (PMID 31906589, 2020). "Directing a lineage‐tracing cassette to the KRT20 locus to track differentiated cells demonstrated that KRT20+ cells can reverse into LGR5+ cells with TIC capacity upon LGR5+‐cell ablation, thereby driving tumor re‐growth." (PMID 28559443, 2017). "An immunohistochemical battery showed the tumor cells to be positive for cytokeratin 7, patchy positive for CA19.9, and patchy CDX2 positive; cytokeratin 20, mesothelial markers, and breast/skin adnexal markers were negative." (PMID 27999702, 2016). "Tumor cells were positive for CK7 EMA, CKAE1/AE3, CD15, CA-125, while immunoreaction for Calretinin, WT1, estrogen, and progesterone receptors, cytokeratin 20, CD10, alpha fetoprotein, CDX2, TTF1, and thyroglobulin were all negative." (PMID 27912770, 2016). "Additional immunohistochemical analysis revealed punctual reaction of the vast majority of tumour cells for keratin MNF 116 with a cytoplasmatic distribution and a punctual perinuclear immune reaction for cytokeratin-20." (PMID 19830210, 2009).
tumor (continued). "Immunohistochemically, the tumor cells are usually positive for low-molecular-weight cytokeratin (CK AE1), predominantly cytokeratin 20 (CK20), neurofilaments and NSE." (PMID 18328106, 2008). "The tumour elements are negative for evidence of cytokeratin 7, cytokeratin 20, and oestrogen receptors." (PMID 39582714, 2024). "Since MCCs are frequently misclassified, today, immunohistochemistry is performed to confirm the diagnosis: a combination of cytokeratin 20 (CK20), neurofilament (NF), CK7 and thyroid transcription factor-1 (TTF-1) stains are used in order to distinguish MCC from other neoplasms." (PMID 37513741, 2023). "It has been reported that molecular detection of tumour markers such as carcinoembryonic antigen (CEA), cytokeratin 19 (CK-19), cytokeratin 20 (CK-20) is better correlated with peritoneal recurrence and associated with adverse outcomes in patients with GC10,17–19." (PMID 35864130, 2022). "Immunohistochemistry for the tumor cells was positive for pancytokeratin and cytokeratin 7, partially positive (up to 20%) for cytokeratin 20 and CDX2, and negative for estrogen receptors, monoclonal carcinoembryonic antigen (CEA), and synaptophysin." (PMID 35664390, 2022). "Using unsupervised hierarchical clustering of six subtyping genes assessed by multiplex RNA hybridization (basal differentiation: KRT5, KRT14, CD44; luminal differentiation: KRT20, GATA3, and FOXA1), 28 tumor samples were each classified as either basal or luminal subtypes." (PMID 36142180, 2022). "Immunohistochemistry revealed that the tumor cells were positive for cytokeratin 7 but negative for cytokeratin 20 and S100 proteins." (PMID 35622762, 2022). "Tumor cells were cytokeratin 7 negative but cytokeratin 20, CDX2, and carcinoembryonic antigen (CEA) positive." (PMID 34514560, 2021). "Interestingly, in the model P8X20, the expression level of 7 markers (i.e., Ki67, KRT5/6, KRT20, 34βE12, PD-L1, EGFR, and Nectin4) was exactly similar between the patient tumor and the next generations." (PMID 35432811, 2021). "A drastic decrease of KRT20 expression after NAC could be observed, suggesting that luminal tumours respond exceptionally well to NAC." (PMID 34073233, 2021). "Also, in the model P8X26, the expression of 8 markers (i.e., Ki67, P63, GATA3, KRT5/6, KRT20, 34βE12, EGFR, and HER2) was similar between the original tumor and different generations." (PMID 35432811, 2021). "Similarly, xenografted patient-derived organoids contain differentiated KRT20+ cells that can re-express LGR5 and fuel tumour regrowth." (PMID 33673710, 2021). "ERBB2-induced gene expression profiles as determined by microarray analysis included cytokeratin 20 (Krt20), Sry-related HMG box gene-17 (Sox17), amphiregulin (Areg), MUC1, and sphingosine kinase 1 (Sphk1) among the genes strongly correlated with tumor growth and metastases of CC cells." (PMID 32708604, 2020). "Evidence of neoplasia in BE and EAC was characterized by reduced gastrointestinal epithelium markers keratin 13 and keratin 20, relative to RE, while epithelial-to-mesenchymal transition markers vimentin and desmin were increased in BE and EAC respectively, compared to control." (PMID 32650561, 2020). "To further investigate the histopathological feature of tumor organoids and how this relates to parental tissues, we performed immunohistochemistry for pancreatic markers KRT7, MUC1 and MUC5AC, and the intestinal markers KRT20 and MUC2." (PMID 33327494, 2020). "Immunohistochemical (IHC) staining was performed using thyroid transcription factor-1 (TTF-1), paired box protein 8 (PAX8), cytokeratin 20 (CK20), caudal-related homeobox transcription factor-2 (CDX-2) and villi protein (Villin) in order to clarify the origin of the tumor." (PMID 32375670, 2020).
tumor (continued). "Immunohistochemical staining revealed that the tumor cells were positive for cytokeratin-7 (CK-7) and Wilms tumor-1 (WT-1) and negative for cytokeratin-20 (CK-20) and estrogen receptor (ER)." (PMID 31222668, 2019). "A minority of tumours originated from the colorectal zone of the anal canal were negative for Krt20 (4/48, 8.3%) or displayed a patchy Krt7 immunoreactivity (5/48, 10.4%)." (PMID 29700411, 2018). "Immunostaining of tumor cells were positive for thyroid transcription factor‐1 (TTF‐1) and cytokeratin 7 (CK7), while negative for caudal‐related homeobox transcription factor 2 (CDX‐2) and cytokeratin 20 (CK‐20), indicating a lung adenocarcinoma origin." (PMID 28781870, 2017). "Immunohistochemically, the tumor cells displayed positivity for keratin 20 and neuroendocrine markers, being negative for keratin 7 and S100 protein." (PMID 26607425, 2015). "The tumor cells were negative for synaptophysin, chromogranin, and cytokeratin 20 by immunohistochemistry, findings which argue against the possibility of primary or metastatic neuroendocrine carcinoma." (PMID 24555117, 2014). "The tumor cells are positive for cytokeratin 7, cytokeratin 20, and CA19-9, and they are negative for TTF-1, CA125, thrombomodulin, and mammaglobin." (PMID 24891967, 2014). "It has been recently reported that cytokeratin 20 positive cells can be detected in the bone marrow aspirates of cystectomy patients, regardless of primary tumor stage." (PMID 22590586, 2012). "In the present study, CDX2 negativity and cytokeratin 20 negativity suggested a non-colorectal origin of the tumor, rather than a colorectal malignancy." (PMID 22074191, 2011). "By immunohistochemistry the tumor cells were cytokeratin 7 positive, cytokeratin 20 negative, and TTF-1 negative." (PMID 21559200, 2011). "The tumor cells were non-immunoreactive for cytokeratin 7, cytokeratin 20, cocktail of cytokeratin AE1/AE3 – Cam 5.2, thyroid transcription factor (TTF-1), leucocyte common antigen (LCA, CD45), and MART-1." (PMID 15967023, 2005). "Moreover, by analyzing FGFR1 mRNA expression, a stromal-rich tumor subtype has been identified that lacks both KRT5 and KRT20 mRNA expression and is almost resistant to upfront chemotherapy (0% pCR rate in FGFR1 high tumors vs. 66.7% pCR rate in FGFR1 low tumors)." (PMID 35887247, 2022). "Moreover, higher pCR in patients with elevated expression of ERBB2, KRT20 or ESR1 may support previous studies showing a lower cancer-specific and relapse-free survival of MIBC patients with high ESR1-expressing tumours." (PMID 34073233, 2021). "However, two of the three keratins associated with the luminal subtype did show only modest (KRT7) or no expression (KRT20) in the tumor transplants." (PMID 30550540, 2018). "The diagnosis of recurrent CRLM was corroborated by the immunohistochemistry that showed negative for cytokeratin 7 and positive for cytokeratin 20, indicating that the segment 4 tumor was CRLM but not intrahepatic cholangiocarcinoma that often develops in cirrhotic liver." (PMID 27234582, 2016). "However, they were negative for other tumor marker immunostains such as desmin, S100 Proteins, cytokeratin 20 (CK20), cytokeratin 7 (CK7), thyroid transcription factor 1 (TTF1) and tumor protein (P63) without any atypical cells." (PMID 25123111, 2014). "The gastro-intestinal tract tumor marker Krt20 was absent in both tumor tissues and all cell lines." (PMID 18507860, 2008). "These tumor cells were negative for Cytokeratin 20, consistent with metastatic mammary carcinoma." (PMID 17020615, 2006). "In addition to its characteristic or aberrant expression in some neoplasms, several lines of evidence suggest that tissue expression of KRT20 may undergo changes in non-transformed epithelia exposed to environmental stressors as well." (PMID 35327321, 2022).
tumor (continued). "In the differential diagnosis with metastatic urothelial carcinoma of the urinary tract, the detection of an associated benign Brenner tumor component, as well as expression of CA125 and absence of cytokeratin 20, may be helpful to confirm a borderline Brenner tumor of primary ovarian origin." (PMID 28025670, 2017). "Tumor cells were positive for cytokeratin 7 (CK7) and GATA3 protein; there was negative staining for cytokeratin 20 (CK20) and mammaglobin." (PMID 38993623, 2024). "The tumor cells were immunoreactive against CD10 and ER but negative for keratin 20 (CK20), CD34, cyclin D1, and SMA." (PMID 33947445, 2021). "The tumor was intensively immunoreactive for cytokeratins 7, AE1/AE3, and BCA225, and focally positive for cytokeratin 20, whereas it was negative for the markers listed in Table EV1 (Fig EV1)." (PMID 32511869, 2020). "The majority of pure pTa HG/papillary pT1(a) HG samples exhibited a luminal-like phenotype, i.e., positivity for KRT20 and a lack of basal cytokeratin (KRT5/6 and KRT14) expression in tumor cells." (PMID 32445084, 2020). "The tumor is negative for EMA, cytokeratin 7, cytokeratin 20, chromogranin A, synaptophysin, S-100 protein, HMB-45, desmin, SMA, EBV, CD117, DOG1, CD23, CD21, clusterin, MDM2, CD34, D240, and ERG." (PMID 31623602, 2019). "Extensive immunohistochemistry staining of the cell block prepared from the pleural effusion sediment in an attempt to find out tumor origin showed that the metastatic adenocarcinoma was positive for cytokeratin 7 (CK7) and negative for cytokeratin 20 (CK20)." (PMID 29729664, 2018). "Tumor cells expressed cytokeratins AE1/AE3 and 7, and were negative for cytokeratin 20, S100 protein, and HMB45." (PMID 29489937, 2018). "Differentiation markers (e.g. KRT20 and PHGR1) can be used to detect small deposits of tumor cells in clinical samples normally negative for such markers, such as lymph nodes from resection specimens." (PMID 29415677, 2018). "These tumours also on the protein level typically showed no or low expression of KRT5 and KRT14, aberrant expression of KRT20 and a low expression of EGFR, but a high expression of ERBB2." (PMID 30258198, 2018). "A histological examination of the resected S6 tumor revealed adenocarcinoma and was confirmed to be CRLM but not intrahepatic cholangiocarcinoma with negative cytokeratin 7 and positive cytokeratin 20 in immunohistochemistry." (PMID 27234582, 2016). "Immunohistochemically, the tumor cells were diffusely positive for pancytokeratin (AE1/AE3), focally positive for lipase and trypsin, and negative for cytokeratin 7, cytokeratin 20, CDX2, and endocrine markers such as chromogranin, synaptophysin, and CD56." (PMID 24550989, 2014). "Tumoral cells from both BxPC-3 CAM tumor and PDAC samples were strongly positive for cytokeratin-7 and -19, CEA and Ki67 but negative for cytokeratin-20 and CD56 (data not shown)." (PMID 24040391, 2013). "Tumor cells were negative for keratin AE1/AE3, keratin 7, keratin 20, epithelial membrane antigen (EMA), CD79a, and immunoglobulin kappa light chain." (PMID 23133774, 2012). "Immunohistochemical analysis evidenced positive reactions with carcinoembryonic antigen (CEA) and cytokeratin 7 in almost all tumor cells, but negative reactions with PSA, CDX2, cytokeratin 20, CA-125 and androgen receptors." (PMID 19468449, 2009). "Although BC tumors with KRT20 overexpression are not suspected of being as menacing as the aggressive KRT5+ MIBC tumors, there is also strong evidence that they can exhibit increased rates of recurrence and tumor progression." (PMID 34771699, 2021).